STAT3 (signal transducer and activator of transcription 3)
Diseases named in the same sentence as STAT3 in open-access papers (continued):
Sharing a sentence is not in itself a finding about the gene and the disease.
gastric cancer (continued). "Mice in which gp130 is mutated and the STAT3 pathway is activated develop gastric cancer." (PMID 26064948, 2015). "The purpose of this study was to determine whether IL-6/STAT3 signaling pathway associates with T lymphocyte changes, and correlates with the progression of human gastric cancer." (PMID 24116074, 2013). "Excessive activation of Stat3 correlates with tumour invasion and metastasis in a variety of cancers and high level of tyrosine-phosphorylated STAT3 is a pertinent feature in colon and gastric cancers associated with adverse outcomes." (PMID 20478049, 2010). "Thus, we infer that the connection between FGFR mutation and STAT3 overexpression and tumor cell resistance may be widely present in a variety of cancers, including gastric cancer." (PMID 39309860, 2024). "It has been reported that SIRT1 counteracts the activation of acetyl-STAT3 (Lys685) and can induce the loss of viability and increase in senescence in gastric cancer (GC) cells." (PMID 34239694, 2021). "In this study, while gastric cancer cells were co-cultured with IL-22-expressing cancer-associated fibroblasts (CAFs) from human gastric cancer tissues, the invasive ability of the gastric cancer cells was significantly enhanced through activation of the STAT3 and ERK signaling pathways." (PMID 26160167, 2015). "Additionally, polymorphisms in STAT3, along with environmental factors, might be associated with the development of gastric cancer." (PMID 24864251, 2014). "However, it still remains unknown how activated STAT3 via interleukin (IL)-6-type cytokine signaling associates with T lymphocyte alteration during the progression of human gastric cancer." (PMID 24116074, 2013). "Studies have shown that in mouse models, inflammation-driven downregulation of EZH2 maintains SASP in CAFs by demethylating the H3K27me3 mark and enhances the formation of peritoneal tumors in gastric cancer (GC) through the JAK/STAT3 signaling pathway." (PMID 40755775, 2025). "In periodontitis, STAT3 signalling activation skews the Th17/Treg balance towards Th17 differentiation, whereas STAT3 inactivation in gastric cancer promotes Th17 differentiation while suppressing Treg differentiation." (PMID 40672112, 2025). "Such protumorigenic effects have been documented in gastric cancer, where B7-H3 modulated the Jak2/STAT3 signaling pathway." (PMID 40214484, 2025). "Propofol, a widely used anesthetic, was shown in a cellular study to induce ferroptosis in gastric cancer cells by upregulating miR-125b-5p, which suppresses STAT3 expression; this effect was reversed upon STAT3 overexpression." (PMID 41226498, 2025). "In gastric cancer tissues, neutrophils produce IL-17A, and TANs-derived IL-17A promotes the migration, invasiveness, and EMT of gastric cancer cells by activating the JAK2/STAT3 pathway." (PMID 40387965, 2025). "Studies on MCL have shown that it suppresses gastric cancer growth by blocking the IL-6/STAT3 pathway." (PMID 40051564, 2025). "In EBV-associated gastric cancers in particular, EHF was up-regulated through a LMPA2 viral protein-mediated activation of STAT3, which resulted in enhanced cell growth." (PMID 41425714, 2025). "Another study indicated that Sorcin promotes migration and invasion and aids in STAT3 activation in gastric cancer cells." (PMID 41228276, 2025). "These inflammatory mediators are pivotal in promoting gastric cancer development through activation of transcription factors, including nuclear factor-κB (NF-κB), signal transducer and activator of transcription 3 (STAT3), and activator protein-1 (AP-1)." (PMID 40940839, 2025). "Gastric cancer patients with high levels of STAT3 as well as miR-21 have a worse prognosis, according to preclinical research." (PMID 41476448, 2025). "Conversely, tRF-33-P4R8YP9LON4VDP inhibits gastric cancer by regulating STAT3 signaling in an AGO2-dependent manner." (PMID 40565315, 2025).
gastric cancer (continued). "Western blotting assays showed the STAT3 expression levels in gastric cancer tissues of mice model group was much higher compared to other two groups." (PMID 41280323, 2025). "The early onset of antral tumors reflects the role of sustained STAT3 activation in human gastric cancer, where this pathway promotes epithelial proliferation, suppresses apoptosis, and creates a tumor-promoting inflammatory microenvironment." (PMID 40673273, 2025). "Calycosin, at a concentration of 50 μmol/L, has been demonstrated to decrease the expression of extracellular signal-regulated kinases, upstream nuclear factor-κB (NF-κB), and signal transducer and activator of transcription 3 (STAT3), in gastric cancer cells." (PMID 40276599, 2025). "tRF-33-P4R8YP9LON4VDP inhibits gastric cancer by regulating STAT3 signaling in an AGO2-dependent manner." (PMID 40565315, 2025). "Mechanistically, gypenoside inhibited the phosphorylation of STAT3, which led to a reduction in PD‐L1 transcription in gastric cancer cells." (PMID 40717210, 2025). "The STAT3 pathway plays a crucial role in gastric cancer progression, promoting cell proliferation, survival, angiogenesis, and metastasis." (PMID 40860906, 2025). "In this study, we provide the first evidence that the combination of DZN and PNR significantly inhibits gastric cancer cell migration and invasion by downregulating STAT3/FAK signaling and suppressing MMP-2 expression." (PMID 40217305, 2025). "The expression profile of STAT3 in gastric cancer tissues from three groups of mice model was examined through Western blotting assays and immunohistochemistry to determine its role in Gastric cancer and its regulatory relationship." (PMID 41280323, 2025). "As a transcriptional factor, STAT3 has been reported to upregulate EZH2 expression and associate with advanced TNM stage and poor prognosis in gastric cancer." (PMID 39917394, 2025). "MicroRNAs such as miR‐124, miR‐223, and miR‐506 have been shown to directly target STAT3 or its upstream activators, suppressing gastric cancer progression." (PMID 40860906, 2025). "Previous studies have established that Stat3 interacts with the promoters of GPX4, SLC7A11, and FTH1, thereby modulating their expression levels in gastric cancer, which leads to the formation of a Stat3-ferroptosis regulatory axis." (PMID 41341590, 2025). "The depletion of IL-6 with a neutralizing antibody or inhibition of the JAK/STAT3 pathway with the specific inhibitor AG490 significantly attenuated these phenotypes in CAF-induced gastric cancer cells." (PMID 40485724, 2025). "JAK/STAT3 inhibitors prevent the increased viability of gastric cancer cells and peritoneal tumor formation induced by senescent CAFs." (PMID 40755775, 2025). "Studies have shown that gastric cancer-derived MSCs activate neutrophils via the IL-6/STAT3 axis, promoting the migration of gastric cancer cells and the formation of endothelial cell tubes in vitro." (PMID 40387965, 2025). "There, miR-92b-5p disrupts the SOCS7-STAT3 interaction, activating STAT3 signaling and inducing the M2 polarization of TAMs, which in turn promotes the proliferation of gastric cancer cells." (PMID 41229433, 2025). "The gp130F/F mutation impairs SOCS3-mediated negative feedback of STAT3 signaling, leading to hyperactivation of the IL-6/STAT3 pathway that is frequently dysregulated in human gastric cancer." (PMID 40673273, 2025). "H. pylori-induced IL-6/IL-11 driving JAK/STAT3 activation plays a major role in the development and progression of gastric cancer." (PMID 40462044, 2025). "Patients with gastric cancer generally have a worse prognosis when their Stat3 levels are high, and this is especially true if the disease has spread to their lymph nodes." (PMID 41476448, 2025). "Targeting and blocking the IL-6/STAT3 pathway therefore represents an effective therapeutic strategy for gastric cancer." (PMID 40051564, 2025).
gastric cancer (continued). "This is consistent with earlier research showing that STAT3 plays a negative regulatory role in the development of gastric cancer." (PMID 40217305, 2025). "A powerful therapeutic target for solid tumors with increased Stat3 activity, miR-21 encourages the development of gastric cancer related to inflammation." (PMID 41476448, 2025). "The current investigation assessed the effectiveness of inhibiting the growth of gastric cancer cells in AGS cells by blocking the JAK/ STAT3 signalling pathways using the natural medicines Concanavalin A (Con-A) and silibinin (SB)." (PMID 40350446, 2025). "NFS1 is a mitochondrial cysteine desulfurase that restricts ferroptosis in gastric cancer by targeting the STAT3 pathway." (PMID 40548711, 2025). "In gastric cancers, loss of PTPRD induced CXCL8 and promoted angiogenic and metastatic events, via STAT3 and ERK signalling pathways." (PMID 40871563, 2025). "In vitro studies have indicated that Sugiol’s interaction with STAT3 potentially inhibits the growth and proliferation of gastric cancer cells (SNU-5)." (PMID 40910010, 2025). "Additional mechanistic studies demonstrated decursin’s capacity to suppress gastric cancer progression via CXCR7/STAT3/c-Myc signaling pathway inhibition and caspase-3-dependent apoptosis induction." (PMID 40508204, 2025). "Apigetrin also inhibits gastric cancer progression by inducing apoptosis and regulating the ROS-modulated STAT3/JAK2 pathway." (PMID 39795089, 2024). "Hongyan Qi and colleagues determined that STAT3 signaling plays a key role in initiating gastric cancer, hyperactivating MSK1 kinase, which phosphorylates histone H3 serine 10 (H3S10) and STAT3, thus establishing a positive feedback loop." (PMID 39309860, 2024). "IL6/GP130/STAT3 signaling promotes malignancy in colon cancer, while in gastric cancer, tumor mesenchymal stromal cells release IL-6 to promote EMT in cancer cells, further spreading the disease." (PMID 38519574, 2024). "For instance, in gastric cancer, STAT3 has been identified as a critical negative regulatory factor of gastric cancer ferroptosis, and its inhibition can suppress gastric tumor growth and alleviate 5-Fu chemotherapy resistance." (PMID 38205151, 2024). "Curcumin can be used to inhibit the activation of JAK/STAT3 signaling pathway in GC, thus overcoming the resistance to chemotherapy in gastric cancer." (PMID 39311951, 2024). "The transcription of miR-26b-5p is suppressed by STAT3; thus, a feedback mechanism is established that increases the proliferation of gastric cancer cells when the level of miR-26b-5p is low or when STAT3 is overactivated." (PMID 39309860, 2024). "This change in expression reveals the critical role played by the β2-AR/STAT3/miR-373 pathway in altering the phenotypic changes in gastric cancer cells, highlighting the role of tailored interventions in affected individuals." (PMID 39309860, 2024). "They performed pharmacologic inhibition (pervanadate) or knockdown of SHP-1 prior to pantoprazole treatment in order to validate the role of SHP-1 in the inhibition of STAT3 activity by pantoprazole in gastric cancer cells." (PMID 39507107, 2024). "The STAT3 signaling pathway plays a pivotal role in the pathogenesis of gastric cancer, promoting tumor proliferation, resistance to therapy, and metastatic progression." (PMID 39309860, 2024). "The potential of these proteins as biomarkers and therapeutic intervention points should be further assessed to elucidate the synergistic effects of survivin and STAT3 on the progression of gastric cancer." (PMID 39309860, 2024). "Similar effects were also found after treatment with the colony-stimulating factor GM-CSF, suggesting a new mechanism of chemotherapy-induced gastric cancer stem cell differentiation and resistance via GM-CSF-miRNA-Jak2/Stat3 signaling." (PMID 39309860, 2024).
gastric cancer (continued). "Lijuan Ma reported that the JAK2/STAT3 signaling axis plays a key role in mediating endoplasmic reticulum stress, thus influencing the response of gastric cancer cells to 5-FU therapy and their autophagic processes, with ATF6 at the operational core." (PMID 39309860, 2024). "CuB combined with cisplatin increased gastric cancer cell cytotoxicity, probably due to enhanced reduction in tyrosine phosphorylation of STAT3 (TYR-705)." (PMID 38397437, 2024). "For example, IL-10 expressed by TAMs was significantly elevated in the tissues and sera of patients with gastric cancer, inducing immunosuppression by regulating the c-Met/STAT3 signaling pathway." (PMID 39840050, 2024). "Nintedanib also induces autophagy-dependent cell death in gastric cancer cells by inhibiting STAT3/Beclin1 cascade signaling." (PMID 38406279, 2024). "In conclusion, gypenoside can downregulate the expression of PD-L1 by inhibiting the translocation of STAT3 phosphate into gastric cancer cells." (PMID 38482051, 2024). "The activation of Twist1 by Rab31 facilitated through STAT3 stimulation and MUC-1 suppression reveals a novel Rab31/STAT3/MUC-1/Twist1/EMT axis implicated in the drug resistance and metastatic potential of gastric cancer." (PMID 39309860, 2024). "First, GC cells significantly contributed to the activation TAM in response to the pro‐inflammatory reaction, which in turn activated NF‐B and STAT3 pathways in cancer cells, leading to the development and progression of gastric cancer." (PMID 38349050, 2024). "STAT3 is known to exert its oncogenic effects and regulate various malignant cell behaviors in gastric cancer by interacting with diverse downstream targets." (PMID 38273295, 2024). "Targeted therapy against IL-6 has shown promising results in mouse models and in vitro cell lines of various cancers, by dampening the IL-6/JAK/STAT3 signaling pathway in gastric cancer, ovarian cancer, and pancreatic cancer." (PMID 38689325, 2024). "By inhibiting the STAT3 signaling pathway, it can decrease the phosphorylation of TYR-705 in STAT3 and inhibit the expression of the STAT3 target gene, thus inhibiting the growth and invasion of gastric cancer cells and inducing the apoptosis of cancer cells." (PMID 39275042, 2024). "The results of our network pharmacological analysis showed that gastric cancer cells treated with gypenoside were significantly correlated with STAT3." (PMID 38482051, 2024). "This leads to a subsequent decrease in the level of STAT3 phosphorylation, thus inhibiting the viability of gastric cancer cells with inactivation of STAT3 and exerting anti-tumor effects 122-123." (PMID 39494324, 2024). "Research indicates that TNF-α derived from gastric cancer induces the production of CD45RA−CCR7+ Treg subsets by activating STAT3 phosphorylation." (PMID 39840050, 2024). "Knockdown of STAT3 or use of the STAT3 inhibitor W1131 can induce ferroptosis through Fe2+ accumulation and lipid peroxidation in gastric cancer cells." (PMID 39396974, 2024). "This article provides an in-depth analysis of the role of STAT3 in gastric cancer, offering a comprehensive foundation for future research aimed at developing novel and effective treatment strategies." (PMID 39309860, 2024). "IL-6 secreted by CAFs has been reported to promote epithelial-mesenchymal transition and metastasis of gastric cancer via the JAK2/STAT3 signaling pathway." (PMID 38510850, 2024). "Overall, these findings indicate that bile reflux and STAT3 activation play pivotal roles in the emergence of gastric cancer." (PMID 39309860, 2024). "ALKBH5 also removes the m6A modification of JAK1 mRNA, leading to upregulation of JAK1 expression mediated by LINC00659 in an m6A-YTHDF2-dependent manner, consequently activating the JAK1/STAT3 pathway in gastric cancer." (PMID 39136000, 2024).
gastric cancer (continued). "In this vein, our study investigated the importance of the Hippo signalling pathway and its crosstalk with gp130/STAT3-mediated inflammatory pathways in gastric cancer development." (PMID 37957015, 2024). "Yi-Ping Liu reported that propofol can block the STAT3 pathway and inhibit the proliferation of gastric cancer cells by increasing the expression of miR-125b-5p." (PMID 39309860, 2024). "Beyond its efficacy in gastric cancer, STAT3 has emerged as a promising target for pancreatic cancer treatment." (PMID 38250721, 2024). "CMTM3 affects EMT progression by inhibiting the EGFR/STAT3 signaling pathway, thereby inhibiting the development of tumorigenesis in chordoma and gastric cancer." (PMID 38223763, 2024). "In Helicobacter pylori infection, inhibition of the JAK2/STAT3 pathway reduces the development of gastric cancer." (PMID 39255287, 2024). "TFF1 impeded the combination of interleukin-6 (IL-6) with IL-6 Rα and further disrupted the activation of STAT3 in the gastric cancer cell lines AGS and STKM2." (PMID 38273295, 2024). "The activation of the IL6/JAK2/STAT3 signaling cascade by SPI1 promotes gastric cancer malignancy and proliferation." (PMID 39309860, 2024). "Previous studies have revealed that PA can trigger STAT3 phosphorylation and exert biological effects in gastric cancer and prostate cancer models." (PMID 38233383, 2024). "The JAK1 upregulation promoted the STAT3 phosphorylation and activated the JAK1/STAT3 pathway, which accelerated the progression of gastric cancer." (PMID 39136000, 2024). "This is due to the activation of a c‐mesenchymal epithelial transition protein/STAT3 signalling pathway by IL‐10 to promote the malignant behaviour of gastric cancer cells." (PMID 38506082, 2024). "Xiongyan Wu and colleagues concluded that cancer-associated fibroblasts (CAFs) isolated from gastric cancer can activate the JAK2/STAT3 pathway in gastric cancer cells by secreting IL-6." (PMID 39309860, 2024). "Correspondingly, increases in the levels of native and phosphorylated STAT3 were detected in gastric cancer tissue, suggesting that survivin and STAT3 are crucial for the progression of this disease." (PMID 39309860, 2024). "In this context, STAT3 acts as a key mediator, increasing the resistance of gastric cancer cells by interacting with several pathways and mechanisms, which are discussed in this article." (PMID 39309860, 2024). "Second, we detected the protein expression of STAT3 and p-STAT3 in gastric cancer cells after gypenoside treatment." (PMID 38482051, 2024). "Recently, studies have found that IL-6 promotes normal macrophages to differentiate into M2 macrophages mediated by STAT3 and therefore supports tumor proliferation in gastric cancer." (PMID 38245798, 2024). "Overexpression of MIR155HG promotes gastric cancer proliferation, migration, and chemoresistance via NF-B and STAT3 (signal transducer and activator of transcription 3) signaling pathways." (PMID 38339237, 2024). "Kyns derived from gastric cancer cells overstimulate regulatory T cells (Tregs) through the IL-10/ signal transducer and activator of transcription 3 (STAT3)/ B-cell lymphoma 2 (BCL2) signaling pathway, promoting chemoresistance." (PMID 38462620, 2024). "As one of the major elements in tumor stroma, gastric cancer‐derived mesenchymal stromal cells (GC‐MSCs) was reported to trigger M2 polarization through activation of the JAK2/STAT3 signaling pathway via high secretion of IL‐6/IL‐8." (PMID 38349050, 2024). "Hongkui Yang and colleagues assessed the link between STAT3 activation and the occurrence of peritoneal metastasis in gastric cancer (GC) patients." (PMID 39309860, 2024).